IFNG (interferon gamma)
Diseases named in the same sentence as IFNG in open-access papers (continued):
Sharing a sentence is not in itself a finding about the gene and the disease.
leishmaniasis (150 papers, 2005 to 2026). Infectious disease that is transmitted through the bite of hematophagous female phlebotomine sand flies. "In leishmaniasis, resistance to infection has been associated with the development of Th1 immune response, with notable amounts of the cytokine interferon gamma (IFN-γ) that are produced mainly by NK and T cells." (PMID 39065160, 2024). "In leishmaniasis, resistance to infection has been associated with the development of a Th1 immune response, with remarkable amounts of interferon gamma (IFN-γ) cytokine that can be mainly produced by NK and T cells." (PMID 33681389, 2021). "Adaptive immunity against leishmaniasis is associated with development of T cell-mediated interferon-gamma (IFN-γ) responses." (PMID 25874567, 2015). "Leishmaniasis associated cytokine profiles (interferon-gamma (IFN-γ) and tumor necrosis factor-alpha (TNF-α among others) were not analyzed." (PMID 26541197, 2015). "A study of the IFNG+874 polymorphism in leishmaniasis patients recorded frequencies of 0.63 and 0.37, respectively, for the A and T alleles in patients with the cutaneous form of the disease, and 0.67 and 0.33 in those with the mucosal form." (PMID 21917128, 2011). "Nonetheless, IL-10 impairs cure of acute leishmaniasis, illustrated in IL-10 deficient mice infected with L. (L.) amazonensis or L. (L.) mexicana which are still unable to eliminate infection despite strong IFNγ production, at least in part through the action of IL-4." (PMID 28629171, 2017). "However, the association of IFNγ+IL-10+ CD4+ T cells with disease progression in leishmaniasis has suggested that through IL-10 production, these cells may contribute to parasite persistence and/or disease pathology." (PMID 22911108, 2012). "A similar scenario was reported in Disseminated Leishmaniasis wherein high levels of IFNγ were accompanied by an increased IgG2, and importantly, was an effective predictor of disease." (PMID 34758028, 2021). "About the effects of thalidomide on Interferon gamma (IFN-γ), an important cytokine in leishmaniasis pathogenesis, some studies demonstrated that an increase in IFN-γ can be observed in response to Thalidomide." (PMID 31492621, 2019). "In preliminary experiments, we suggested the participation of CD4+ T cells to produce Interferon-gamma in LaAg vaccine, as indicated for several studies as the most important Th1 parasitic-specific response against leishmaniasis." (PMID 27716449, 2016). "In leishmaniasis, phagocytes are stimulated to produce IL-10, which leads to a reduced production of cytokines related to the Th1 profile, such as IL-12 and interferon gamma (IFN-γ)." (PMID 26538837, 2015). "IFNG mediates host protection against leishmaniasis, exerting its pleotropic effect in macrophage activation and killing Leishmania parasites through induction of nitric oxide." (PMID 25466928, 2014). "Even though CD8 cells seem to be dispensable for overall protection against the infection, early IFNγ production by CD8 cells was proposed to favor the Th1 immune response during leishmaniasis." (PMID 23028548, 2012). "It has been also demonstrated that CD4+ T cells that expresses IFNγ and TNFα play an important role in therapy against leishmaniasis." (PMID 22715418, 2012). "CD8 T cells have been shown to exert a curative role in murine models of leishmaniasis, which has been attributed to the production of IFNγ as well as a potential role for perforin (CTL function)." (PMID 21695103, 2011). "Self-healing forms of leishmaniasis and cure of VL is typically accompanied by parasite specific proliferation and IFNγ production." (PMID 20606969, 2010). "Yet thus far, the important role of CD8 in leishmaniasis has been related to their IFNγ production and little is known of the protective response mediated by the cytotoxicity exerted by these cells." (PMID 21072232, 2010).
leishmaniasis (continued). "Although not much is known of the overall effector mechanisms of CD8 T cells in human leishmaniasis, results obtained in the present work show that both IFNγ production, as well as cytotoxicity against Leishmania-infected macrophages are hampered in DCL cells." (PMID 21072232, 2010). "In all forms of leishmaniasis, a cure is affected through a cellular immune response involving interferon gamma (IFN-γ) that activates host macrophages to eliminate the parasite." (PMID 23554607, 2010). "Early studies of experimental leishmaniasis in C3H/HeN mice indicated that IFNγ production by NK cells was important for generation of protective immune responses and control of infection." (PMID 20606969, 2010). "In leishmaniasis, cytokines such as interferon-gamma (IFN-γ) and tumor necrosis factor alpha (TNF-α) have a major role in controlling intracellular growth of the etiological pathogen." (PMID 17456233, 2007). "IFNγ role in leishmaniasis is well known, increasing macrophages’ ability to destroy parasites." (PMID 33617528, 2021). "Likewise, for every one pg/mL increase in plasma IFNγ and every one mm increase in LST, the risk of having leishmaniasis declined by 0.24% and 14.11%, respectively." (PMID 28611427, 2017). "Leishmania recognition by monocytes or macrophages through TLRs leads to the production of proinflammatory cytokines such as tumor necrosis factor (TNFα), interleukin (IL)-6, and interferon gamma (IFNγ), which all contribute for the exacerbated inflammation in leishmaniasis lesions." (PMID 29123157, 2017). "Another reported function of CD8 T cells in leishmaniasis is IFNγ production." (PMID 21072232, 2010). "Our results demonstrate that IFNG +874T/A SNP could be involved in the pathogenesis of leishmaniasis by influencing the amount of IFN-γ released by CL patients, although it could not prevent disease development." (PMID 17456233, 2007). "Despite this, IFNG +874T/A SNP could be involved in the pathogenesis of leishmaniasis by influencing the amount of cytokine released by CL patients, although it could not prevent disease development." (PMID 17456233, 2007). "Of note, vaccination simulation with LeishChim induced production of IFNγ in higher levels compared to IL-10, suggesting that vaccination with LeishChim could induce the TH1-type immune response that is protective against leishmaniasis." (PMID 36851182, 2023). "For example, while greater inflammation is seen in leishmaniasis when the host IFN response is induced by parasites harboring Leishmania RNA virus (LRV) others have found TLR4 mediated NFκB activation to be unaffected by IFNγ." (PMID 31293585, 2019). "The co-production of IL-10 by IFNγ-producing CD4+ T cells is not novel for leishmaniasis, however, and is now a recognized feature of Th1 cell differentiation." (PMID 22911108, 2012).
Crohn disease (145 papers, 2008 to 2026). A gastrointestinal disorder characterized by chronic inflammation involving all layers of the intestinal wall, noncaseating granulomas affecting the intestinal wall and regional lymph nodes, and transmural fibrosis. "Mucosal enrichment of the Adherent-Invasive E. coli (AIEC) pathotype and the expansion of pathogenic IFNγ-producing Th17 (pTh17) cells have been linked to Crohn’s Disease (CD) pathogenesis." (PMID 39069911, 2024). "The ulcerative colitis severity region-associated rs1861494 T allele in IFNG was associated with this IFNG promoter methylation loss, and more severe disease outcomes in both ulcerative colitis and Crohn’s disease." (PMID 31159831, 2019). "While we noted shared enriched signatures for adaptive immune-related pathways and interferon gamma, we also identified more unique Crohn disease associated and Celiac disease associated enriched pathways." (PMID 31700112, 2019). "Tbx21 expression is implicated in the abnormal expression of IFNγ in Crohn’s disease and GATA-3 is involved in the immunopathology of ulcerative colitis." (PMID 27530627, 2016). "The reduction of IFNγ in Crohn’s disease is linked to the clinical response to these agents." (PMID 24115947, 2013). "Patients with Crohn’s disease, who were administered high doses of IL-10, experienced increased inflammation due to elevated levels of Interferon-gamma (IFN-γ)." (PMID 40761632, 2025). "Current research has implicated a close correlation between key ferroptosis-related genes such as TIMP1, CAV1, CD44, HIF1A, and IFNG, and immune infiltration in Crohn’s disease." (PMID 40687427, 2025). "Claudin-5 redistribution was also found in colon biopsies of patients with Crohn’s disease or lymphocytic colitis and was mimicked by TNFα and IFNγ in colon epithelial cell lines in vitro." (PMID 40438590, 2025). "IFNβ- and IFNγ-polarized macrophages aligned with cluster 3, which best represented macrophages from areas of active Crohn’s disease." (PMID 41425579, 2025). "IFNγ+ ILC1s were accumulated in the intestine of Crohn’s disease patients with low expression levels of TET1 and TGFBR1." (PMID 38839760, 2024). "The analysis demonstrated an increase in inflammatory response, IFNα response, IFNγ response, and TNFα signaling via NF‐κB in the colonic epithelium of both patients with ulcerative colitis and Crohn's disease compared to their normal counterparts." (PMID 39378064, 2024). "We highlight the possible role of IFNγ-treated macrophages in the complications related to Crohn’s disease." (PMID 35625832, 2022). "In individuals with Crohn’s disease, T-bet+ B cell numbers correlate with IFNγ+ T cell numbers in the gut." (PMID 35298565, 2022). "Further, culturing ABC-like cells from individuals with Crohn’s disease with autologous CD4+ T cells results in the production of IFNγ and IL-12 by the T cells." (PMID 35298565, 2022). "Crohn’s disease and celiac disease are type IV hypersensitivity reactions which involve IFNγ and cytotoxic lymphocytes." (PMID 33924586, 2021). "In studies in Crohn’s disease with human IL-10 treatment, higher dose IL-10 treatment led to elevated levels of inflammatory mediators, specifically IFNγ and TNFα." (PMID 30249047, 2018). "In the present study, the population of CD39 expressing CD8+ T cells in healthy controls, as well as those in Crohn's disease, can be shown to produce preferentially greater levels of IFNγ on a per-cell basis." (PMID 26549640, 2015). "Neutralizing TNFα or IFNγ, two cytokines central to Crohn’s disease, can prevent this abnormal intestinal injury specific to MNV-infected Atg16L1HM mice." (PMID 21994779, 2011). "One study strengthened the argument that LRRK2 is a Crohn’s disease gene by demonstrating that this gene is regulated by IFNγ and expressed in immune cells in the mucosa of patients." (PMID 21994779, 2011). "This IFNγ-positive IL-17-positive subset is particularly enriched in the gut of patients with Crohn's disease." (PMID 20929536, 2010).
Crohn disease (continued). "Indeed, long-term exposure to inflammatory cytokines such as IL-1, IL-6, IL-8, TNF-α and interferon-gamma (IFN-γ) is linked to several illnesses, including IBD which include ulcerative colitis (UC) and Crohn’s disease (CD)." (PMID 37743919, 2023). "In Crohn’s disease (CD), it is the combined effects of Interferon-gamma (IFNγ) and TNF-α that lead to epithelial injury, leading to a reduction in the number of connections at the tight junctions, breaks in them and alteration of protein content and composition of these junctions." (PMID 33499333, 2021). "Interestingly, GSK2256294 reduced IL4 and IFNγ in ulcerative colitis, and IL1β in Crohn's disease specifically, suggesting potential differential effects of GSK2256294 in these two diseases." (PMID 31002701, 2019). "We can show that treatment with NOX inhibitor blocks IFNγ production and diminishes Tc1 responses in Crohn's disease, perhaps indicating that inhibition of NOX2/ROS signalling could be further explored as a potential therapeutic target." (PMID 26549640, 2015). "Death associated protein (DAP or DAP1) has been linked with ulcerative colitis rather than Crohn’s disease, and encodes a ubiquitously expressed protein originally identified in a screen for factors involved in IFNγ-induced apoptosis." (PMID 21994779, 2011). "Similarly, high-dose IL-10 in Crohn’s disease patients increased IFNγ production." (PMID 39502968, 2024). "Moreover, whether such cellular signals modulate IFNγ production of Tc1 cells in Crohn's disease remains largely unexplored." (PMID 26549640, 2015). "For patients with either Crohn’s disease or UC, Th17 cells are abundant in inflamed intestine terminal ileum and produce IL17A, IL17F, IL26 and IFNγ." (PMID 34390759, 2021). "The pathway modulates interferon gamma, which induces the JAK/STAT pathway that is involved in Crohn’s disease." (PMID 27622767, 2016). "A2A receptor signalling following use of adenosine or/and more specific agonists, for example, CGS21680, decreased IFNγ production of both blood and lamina propria CD8+ T cells from Crohn's disease patients in vitro." (PMID 26549640, 2015). "Intriguingly, blockade of NOX/ROS by DPI markedly abrogated IFNγ production in blood and lamina propria CD8+ T cells obtained from patients with active Crohn's disease." (PMID 26549640, 2015). "Interestingly, IFNγ and TNF-producing ILC1s are increased in the intestinal tissue of Crohn’s disease patients, where TNF together with IFNγ can increase permeability of the intestinal epithelial barrier leading to exacerbation of inflammation." (PMID 36969171, 2023). "Indeed, the group 1 signature, which characterizes two of the three Crohn’s disease CI-enriched clusters, is enriched for genes that positively regulate proinflammatory cytokines TNF and in interferon-gamma (IFNɣ)." (PMID 36313344, 2022). "Interestingly, Crohn’s disease ASCs induced a marked reduction on lymphocytes’ viability, which was maintained with OVA and IFNγ treatments, and is in accordance with the link between proliferation and apoptosis described for activated lymphocytes." (PMID 33924264, 2021). "Moreover, Crohn's disease patients exhibit markedly increased expression of IL15 and IFNγ in the inflamed colon compared with healthy people, indicating that NK1.1+CD8+ T cells involved in intestinal inflammation in Yeti mice might be physiologically relevant to the development of Crohn's disease." (PMID 30333822, 2018).
dengue (145 papers, 2005 to 2025). "In DENV-2 genotype, T164S mutation in NS1 protein ascertains the fact that mutation in dengue protein can enhance clinical severity, as well as increased Th1 response—IL-6, IFNγ, and TNFα—in in vivo and in vitro experimental model." (PMID 34447698, 2021). "In support of this, greater numbers of dengue specific CD8s producing TNFα, IFNγ, and IL-2 prior to heterotypic infection was associated with an asymptomatic infection." (PMID 31816907, 2019). "Using an 8-color flow cytometry panel, we then measured the number of CD3+ CD4+ or CD3+ CD8+ T cells producing cytokines that have been implicated in natural dengue disease: IFNγ, TNFα, IL2, and IL10." (PMID 22816004, 2012). "Proinflammatory cytokines such as TNFα, IFNγ, and IL-6 have been associated with severe secondary dengue disease in several studies." (PMID 22816004, 2012). "A growing body of evidence indicates that the production of IFN-γ is regulated by single nucleotide polymorphisms (SNPs) within the IFNG gene, which may influence host susceptibility to a large range of diseases including dengue." (PMID 33445752, 2021). "Indeed, we could observe that individuals with dengue with warning signs or severe dengue displayed lower activation of T cells associated with increased innate immunity cytokine production, including IFNg production by ILC1." (PMID 35335618, 2022). "Synthetic glucosidase inhibitors (DNJ derivatives) have been reported to modulate Interferon gamma and TNFα receptor signalling in Dengue virus infection in primary human macrophages; this is possibly related to N-linked glycosylation changes." (PMID 35630818, 2022). "Some reports favor that IFNγ protects from dengue infection; while others say it contributes to dengue pathogenesis." (PMID 34447698, 2021). "In dengue severity, Th1 cytokines GM-CSF and IFNγ antagonize Th2 cytokines IL-10 and IL-4, respectively, for the progression towards DHF/DSS." (PMID 34447698, 2021). "In dengue fatalities, histopathology shows the virus triggered the pro-inflammatory cytokines TNFα along with IFNγ by mononuclear cell infiltration in liver, lung, and kidney, which is evidence for cytokine storm–induced pathogenesis in dengue." (PMID 34447698, 2021). "For instance, NS3-specific CD8+ T cells from donors with severe dengue had a higher production of tumor necrosis factor (TNF) vs. IFNγ compared with children with mild dengue." (PMID 31244855, 2019). "A higher magnitude of IFNγ response to DENV NS1 was found in experienced dengue donors, but a hyporesponsiveness was found in any acute viruses, even experiencing dengue." (PMID 29282904, 2018). "Blood samples were obtained after each immunization and various time points thereafter to assess anti-dengue antibody and interferon gamma (IFNγ) T-cell immune responses." (PMID 29363446, 2018). "Several of these cytokines have been identified as markers of dengue in humans, including IL-12, IL-13, IL-17A, G-CSF, IFNγ, and TNFα." (PMID 29559699, 2018). "An earlier Phase 1 clinical trial of a prototype monovalent dengue-1 DNA vaccine showed the vaccine to be well tolerated and capable of generating good anti-dengue IFNγ T-cell responses, but poor anti-dengue neutralizing antibody responses." (PMID 29363446, 2018). "We used this ex vivo ELISPOT method to model antigen presentation of dengue-derived peptides to antigen-specific T cells in vitro and assessed T cell activation by IFNγ production, as a representative cytokine produced by T cells during dengue infection." (PMID 30273352, 2018). "We conclude that TVDV was safe and well-tolerated and elicited predominately anti-dengue T-cell IFNγ responses in a dose-related fashion." (PMID 29363446, 2018). "Whereas anti-dengue IFNγ T-cell responses occurred in most of the study subjects, anti-dengue neutralizing antibody responses were poor." (PMID 29363446, 2018). "Even though IFNγ plasma levels were correlated with dengue severity, in our work, IL12 levels were enhanced in mild cases." (PMID 29038620, 2017).